BRD4 (bromodomain containing 4)
Diseases named in the same sentence as BRD4 in open-access papers (continued):
Sharing a sentence is not in itself a finding about the gene and the disease.
prostate carcinoma (continued). "By physically interacting with AR NTD, BRD4 plays a critical role in facilitating AR-mediated transcription; clinical evaluation of BET inhibitors is currently underway in castration-resistant prostate cancer (clinical trial: NCT03035591)." (PMID 34417184, 2021). "Besides, the protein level of BRD4 has a significant effect on BET inhibitors, and this process is regulated by the activity of SPOP, which degrades BRD4 in prostate cancer cells." (PMID 31718704, 2019). "In addition to over-riding programmed cell death responses via upregulation of anti-apoptotic factors, CDK9 also promotes the expression and/or activity of oncogenic transcription factors such as MYC, NF-κB, BRD4, and STAT3, all of which are established drivers of prostate cancer progression." (PMID 39117800, 2024). "Therefore, elevated expression of BRD4 and MYC confer JQ1 resistance in prostate cancers." (PMID 37036970, 2023). "Besides, SPOP-mutant prostate cancers often accumulate BET proteins, including BRD2, BRD3 and BRD4." (PMID 36357379, 2022). "Therefore, DUB3 inhibitors may promote the degradation of BRD4 and reverse the drug resistance effect of JQ1 in prostate cancer." (PMID 34454495, 2021). "However, targeted disruption of BRD4 function also results in tumor cell killing in a variety of solid tumors where MYC does not appear to be a major cancer driver, including certain lung cancers, prostate cancers, and glioblastoma." (PMID 32796829, 2020). "We show that in 22Rv1 prostate cancer cells, EZH2 occupies a large set of gene loci lacking H3K27me3, and these non-canonical genomic sites are instead co-occupied by p300, RNA Polymerase II and BRD4 and are rich in histone marks associated with transcriptional activation." (PMID 40534232, 2025). "Endometrial cancer–associated SPOP mutations preferentially degrade BET proteins, while prostate-cancer–specific SPOP mutation results in impaired degradation of BET proteins, as mutations of SPOP degrons in BRD4 determine whether they bind BET proteins or not, thus influencing BET ubiquitination." (PMID 34540900, 2021). "Additionally, BRD4 closely regulates non-homologous end-joining repair (NHEJ) and has been observed to be necessary for the NHEJ repair of radiation-induced double-stranded breaks in prostate cancer." (PMID 40649963, 2025).
leukemia (110 papers, 2012 to 2025). A malignant (clonal) hematologic disorder, involving hematopoietic stem cells and characterized by the presence of primitive or atypical myeloid or lymphoid cells in the bone marrow and the blood. "The expression levels of hnRNPK, NSUN1 and BRD4 were also linked to leukaemia progression and implicated in both 5‐AZA resistance and cancer advancement." (PMID 40008496, 2025). "In KMT2Ar leukemias, BRD4 is often associated with super-enhancers that drive the expression of oncogenes such as MYC, BCL2, and CDK6, which are vital for leukemic cell survival and proliferation." (PMID 39682203, 2024). "The expression levels of hnRNPK, NSUN1, and BRD4 are associated with leukemia progression and contribute to 5‐AZA resistance and tumor development." (PMID 39445003, 2024). "Reportedly, in AML, inhibition of Brd4 causes end-myeloid differentiation and leukemia stem cell elimination." (PMID 37745860, 2023). "Genome-wide loss-of-function clustered regularly interspaced short palindromic repeats (CRISPR) screens identify SPOP gene deficiency as a resistance factor to BRD4 inhibitor therapy in KMT2A gene-rearranged leukemia cells." (PMID 38135679, 2023). "BRD4 has been reported as a required target for leukemia progression by promoting a cancer-associated transcriptional program." (PMID 32674429, 2020). "We performed NGS to try to identify mutations/alterations that are responsible for formation of the NSUN1-/BRD4-associated 5-AZA-resistant chromatin structure in leukaemia cells." (PMID 29563491, 2018). "For example, TGF-β1, BCL3 and BRD4, which all have been linked with leukemia development were overlooked by the RD protocol." (PMID 28818039, 2017). "Similar observations have been shown in DNMT3A (DNA methyltransferase 3A) mutated leukemia where JQ1 inhibits the action of BRD4 and induces caspase 3/7-mediated apoptosis." (PMID 26830473, 2016). "Med-1, a mediator of RNAPII transcription and interactor of the bromodomain protein 4 (BRD4), an SE assembly protein, was recently implicated in leukemia chemoresistance via interaction with LEDGF/p75 and in enhancing the stemness and metastasis of squamous cell carcinoma via SE formation." (PMID 34685704, 2021). "Specifically, NSUN1 collaborates with BRD4 to establish a distinctive NSUN1/BRD4/RNA‐pol‐II CTD‐S2P complex in leukaemia cells resistant to 5‐AZA." (PMID 40008496, 2025). "CHD8 was previously shown to bind BRD4 via NSD3 in leukemia cells and act as a functional CHD8-NSD3-BRD4 unit in transcriptional activation." (PMID 40104050, 2025). "MZ1, a selective BRD4 degrader, has demonstrated superior efficacy in triple-negative breast cancer and leukemia models, suggesting a potential role in overcoming resistance to small-molecule BET inhibitors." (PMID 41335282, 2025). "Previous findings also suggested that ZMYND8 is essential for AML survival by binding to the ET domain of BRD4 through its chromatin reader domain, thereby sustaining leukemia growth." (PMID 40223119, 2025). "Our previous study demonstrated that a bromodomain protein 4 (BRD4) inhibitor can revise the phenotype and function of exhausted T cells from leukemia patients." (PMID 39407311, 2024). "Brd4 acts as an oncogene in the development of cancers, such as squamous cell carcinoma, leukemia, CRC, and breast adenocarcinoma by detecting DNA damage, activating, repairing, and maintaining telomeres." (PMID 37745860, 2023). "General targeting of SEs with BRD4 inhibitors has shown efficiency, in particular in cancers with specific SE single mutation alterations or with the activation of MYC SE in leukemia or lymphoma." (PMID 36944729, 2023). "Brd4 is also a transcription factor for c‐Myc and Bcl2, and Brd4 inhibition induces apoptosis of leukemia cells." (PMID 35132816, 2022).
leukemia (continued). "Inhibition of BET bromodomain function by the inhibitor I-BET151 impaired the recruitment of BRD4, P-TEFb, and PAF1 to the TSS of selected genes in human HL60 leukemia cells, and provided evidence for an interaction of BRD4 with the super elongation complex." (PMID 36047906, 2022). "In 5-AZA-resistant leukemia cells (ARLC), the interaction of NOP2, BRD4, and RNA pol-II is associated with the formation of an active chromatin structure with resistance to 5-AZA but is highly sensitive to the inhibition of BRD4 and NOP2." (PMID 35562754, 2022). "Based on the important role of BRD4 in regulating leukemia gene transcription along with NF-κB, BRD4 specific inhibitors JQ1 (thieno-triazolo-1,4-diazepine) and IBET-151 have been tested for AML treatment." (PMID 35884618, 2022). "For instance, a mechanism involving Wnt/β-catenin, Hedgehog, MAPK signaling or TGF-β pathway compensates for the effects of BRD4 inhibition on MYC expression or protein stability in leukemia, hepatocellular carcinoma, and pancreatic and colorectal cancer." (PMID 35408939, 2022). "Similar to PAN, inhibition of BRD4 in vitro by JQ1 (but also by BRD4 shRNA) led to apoptosis of a panel of leukemia lines, and this effect was simultaneously enhanced in the presence of AZA." (PMID 35053339, 2022). "In SEM leukemia cell lines, BRD4 inhibition has only minor effects on enhancer-promoter interactions, despite a strong effect on key oncogenic target gene expression." (PMID 35362516, 2022). "Nitroxoline is an antibiotic that showed potential over BRD4 with inhibitory activity against leukaemia cell lines, and has been shown to be effective against leukaemia cell lines." (PMID 34471498, 2021). "A recent study reported that combined CDK7/12/13 inhibition with THZ1 and BRD4 inhibition overcomes enhancer reprogramming in BET inhibitor-resistant leukemia cells and consequently suppresses oncogenic transcription." (PMID 35198433, 2021). "I-BET151 exerts anti-leukemia activity by decreasing the presence of BRD4 and CDK8 in the enhancer region and downregulating the genes related to super-enhancers (SEs)." (PMID 34540687, 2021). "Our preliminary in vivo results show that dual inhibition of PI3Kδ and BRD4 led to a reduction of leukemia cell numbers in the peripheral blood of leukemia bearing mice." (PMID 34926269, 2021). "Brd4 was identified as a promising therapeutic target for AML, and targeting Brd4 using small hairpin RNAs or small molecule inhibitors resulted in a strong anti-leukemia effect, terminal myeloid differentiation and elimination of LSCs." (PMID 34012921, 2021). "To validate this possibility, we carried out a well-established combinatorial assay on leukemia cells with increasing doses of I-BET151 (a BRD4 inhibitor) and/or THZ1 (a CDK7 inhibitor)." (PMID 32029739, 2020). "dBET1 treatment induces strong BRD4 degradation, resulting in apoptosis of leukemia cell lines as well as ex vivo leukemic cells." (PMID 32674429, 2020). "Since activation of the BRD4-dependent gene expression is a core oncogenic driver for leukemia diseases and Burkitt’s lymphoma, we also analyzed BRD4′s phosphorylation status in a number of leukemia and lymphoma cell lines." (PMID 32575711, 2020). "The expression levels of hnRNPK, NSUN1 and BRD4 were correlated with the course of leukemia and were involved in 5-AZA resistance and cancer development." (PMID 32944246, 2020).
leukemia (continued). "This BRD4-independt de novo enhancer restored the enhancer-promoter looping at the MYC locus to drive MYC transcription in BETi-resistant leukemia cells." (PMID 32029739, 2020). "Macrocyclic PROTAC-1, a derivative of MZ1, showed strong and selective BRD4 degradation and potent anti-proliferation activity in several leukemia cells." (PMID 32404196, 2020). "By contrast, single knockdown of BRD4 was sufficient to suppress the growth of BETi-sensitive leukemia cells in vitro (blue curves)." (PMID 32029739, 2020). "In this study, we discovered a strong synergistic lethality of targeting the reprogrammed enhancers in BETi-resistant leukemia cells by suppressing BRD4 and CDK7 activity in vitro and in vivo." (PMID 32029739, 2020). "Previous studies suggested that ARV-825 can more efficiently decrease the expression of BRD4 and the proliferation of leukemia cells than dBET130,31." (PMID 32080280, 2020). "Upon irradiation, it robustly decreased BRD4 in leukemia RS4;11 cells and showed a potent anti-proliferation activity." (PMID 32404196, 2020). "Brd4 is a validated drug target in leukemia and Brd4 chromatin occupancy in AML correlates with the transcriptional activation of a number of essential hematopoietic transcription factors." (PMID 29545928, 2018). "Di-methylation of H3K79 mediated by DOT1L is involved in this process, as described in MLL leukemia, suggesting an unrecognized functional interplay between BRD4 and DOT1L." (PMID 28804523, 2017). "It has been shown that hematopoietic LDTFs and CBP/p300 facilitate Brd4 recruitment to active enhancers in leukemia cells." (PMID 29263365, 2017). "The effects of targeted degradation of BRD4 were investigated in vivo following intraperitoneal dosing of dBET1 to mice bearing xenograft human MV4-11 leukaemia cells." (PMID 28298557, 2017). "The bromodomain protein Brd4 is an epigenetic reader and plays a critical role in the development and maintenance of leukemia." (PMID 28490802, 2017). "A pioneering functional genomics screening of chromatin regulators in MLL-rearranged leukemia unveiled a role for BRD4 in maintenance of C-MYC expression and leukemia oncogenicity." (PMID 29075615, 2017). "Brd4 is one of the most well-studied bromodomain-containing proteins playing critical roles in c-Myc hyperactivation and leukemia cell proliferation." (PMID 27764789, 2016). "To further demonstrate the site-specific role of proline hydroxylation on leukemia cell activity, we generated a Brd4 mutant plasmid with P536A through site-directed mutagenesis and identified an shRNA targeting 3′UTR to knock down the endogenous Brd4." (PMID 27764789, 2016). "We selected MV-4,11 cells as a model, which is a leukemia cell line highly dependent on Brd4 transcription activity and very sensitive to Brd4 inhibitor JQ1." (PMID 27764789, 2016). "Brd4 is a key transcription factor that has been recently identified to play an important role in leukemia cell proliferation." (PMID 27764789, 2016). "To evaluate the importance of c-Myc expression, we treated MLL-FP cell lines with the BET inhibitor JQ1, which inhibits the proliferation of multiple forms of leukemia by disrupting BRD4 regulation of c-Myc and other factors such as Myb and Ets proteins." (PMID 27007052, 2016). "The BRD4 inhibitor inhibits MLLr leukemia by destabilizing ETS family transcription factors in hematopoietic cells and disrupting pTEFb-dependent gene regulation." (PMID 27462455, 2016). "c-MYC has been shown to be regulated by BRD4 in various cancer cell lines such as Hela cells and leukemia cells, and c-MYC expression was reduced upon BRD4 knockdown or cell treatment with small molecules inhibiting BRD4." (PMID 26830473, 2016). "Inhibition of prolyl hydroxylase activities significantly diminished the expression of Brd4-targeted genes as well as the proliferation of leukemia cells." (PMID 27764789, 2016).
leukemia (continued). "The bromodomain (BRD) and extraterminal (BET) proteins including BRD2, BRD3 and BRD4 have been identified as key targets for leukemia maintenance." (PMID 25989842, 2015). "This sensitivity for BRD4 inhibition seems to stem from a sort of epigenetic addiction to superenhancers characteristic of leukaemia and appears to be a more general feature of cancers, independent from the underlying genetic anomaly." (PMID 25183998, 2014). "Recent exciting work has also identified highly specific inhibitors of the BET family of Bromodomain containing proteins (including BRD4) as effective inhibitors of a range of different leukemias, including those containing MLL-FPs." (PMID 24213472, 2012). "Thus, depending on the leukemia cell type, both BRD4 and Myc can become dispensable under certain conditions." (PMID 38201575, 2023). "It was recently shown that inhibition of BRD4 suppresses leukemia progression." (PMID 35053339, 2022). "Thus, we revealed that BRD4 inhibition exerts an anti-leukemia effect through the PD-1-regulatory pathway in AML." (PMID 35918330, 2022). "Importantly, the MLL-BRD4 complex binds to histone acetylation marks to recruit POL II in order to control transcriptional elongation, and a small molecule inhibitor of BRD4 (i-BET) has shown promise for use in MLL leukemia therapy." (PMID 33143730, 2020). "However, when we compared Encode data for the K257 leukemia cell line using the GSM2527370 data for MITF and the GSM2700494 data for BRD4, we found 6937 MITF peaks and 8509 BRD4 peaks, with 1204 overlapping between MITF and BRD4." (PMID 32151278, 2020). "The current hypothesis for the effect of BRD4 inhibitor treatment against leukemia is that the action of key developmental transcription factors, such as MYC, is blocked upon BRD4 inhibition." (PMID 32382029, 2020). "One possible mechanism is the truncated ASXL1 could interact with BRD4, leading to the openness of chromatin in leukemia cells." (PMID 32669118, 2020). "Genetic and shRNA-mediated silencing of BRD4 in MLL-AF9 driven leukemia models not only resulted in the removal of BRD4 from super-enhancers, including the MYC enhancer, but also in differentiation of leukemia cells and decrease of leukemogenic potential in vitro and in vivo." (PMID 31552175, 2019). "Furthermore, the inhibition of BRD4 in vitro with JQ1 or shRNA induced leukemia cell apoptosis, especially when combined to azacitidine, and triggered the activation of the DNA damage response pathway." (PMID 30761268, 2019). "Both 5-AZA-resistant leukaemia cell lines and clinically 5-AZA-resistant myelodysplastic syndrome and acute myeloid leukaemia specimens have a significant increase in RNA:m5C and NSUN1-/BRD4-associated active chromatin." (PMID 29563491, 2018). "NSUN1 specifically interacted with BRD4 in the 5-AZA-resistant M2AR leukaemia cells." (PMID 29563491, 2018). "Since Brd4 transcriptional activity has been shown to be critical for AML cell proliferation and survival, we next asked whether the altered Brd4 transcription activity by prolyl hydroxylase inhibitors will affect leukemia cell growth." (PMID 27764789, 2016). "BRD4's capacity to heighten Myc levels thus probably extends over almost all leukaemias." (PMID 23303309, 2013). "BRD4 in particular has been identified as a key therapeutic target in AML based on an RNAi screen of epigenetic genes in an mixed lineage leukemia (MLL) fusion leukemia mouse model." (PMID 24403256, 2013).